GPC3 (glypican 3)
Diseases named in the same sentence as GPC3 in open-access papers (continued):
Sharing a sentence is not in itself a finding about the gene and the disease.
tumor (continued). "The 32A9 immunotoxin exhibited specific cytotoxicity to GPC3-positive cancer cells, while 32A9 CAR-T cells efficiently eliminated GPC3-positive HCC cells in vitro and caused HCC xenograft tumor regressions in vivo." (PMID 32746924, 2020). "The prognostic significance of tumor cell serum GPC3 levels and GPC3 immunoreactivity in patients with HCC has been already established." (PMID 33643907, 2020). "The prognostic value of serum GPC3 level and tumor cell GPC3 immunoreactivity as a biomarker has already been well established in patients with HCC." (PMID 33643907, 2020). "Currently, and the role of GPC3 in tumorigenesis and its biological functions is poorly understood and many possible mechanisms regulated by GPC3 during tumorigenesis and tumor progression should be suggested." (PMID 32582830, 2020). "Statistically,the expression of GPC3 was significantly higher in samples with larger tumor size (p= 0.03)." (PMID 32582830, 2020). "G12msi showed significant anti-tumor effects against GPC3-overexpressing HCC tumors both in the in vitro and in vivo models." (PMID 33080969, 2020). "We found that G12msi binds to GPC3-overexpressing HCC tumor cells with high specificity and is effectively internalized." (PMID 33080969, 2020). "G12msi aptamer treatment dose-dependently inhibited tumor growth in the mice bearing GPC3-overexpressing HepG2 cells." (PMID 33080969, 2020). "GPC3 can promote tumor growth by stimulation of canonical Wnt signaling via making a complex with Wnt molecules." (PMID 32582830, 2020). "Herein, we developed G12msi, a gemcitabine-incorporated DNA aptamer, targeting GPC3, and evaluated its binding specificity and anti-tumor efficacy in GPC3-overexpressing HCC cell lines and murine xenograft models." (PMID 33080969, 2020). "Tumor formation was associated with upregulated mRNA expression of the established HCC tumor markers AFP and GPC3." (PMID 33400730, 2020). "Lastly, although serum des-gamma-carboxyl prothrombin and glypican-3 were important tumor markers for HCC development, the prognostic performance of the two markers was not considered in this study." (PMID 33198216, 2020). "Previous studies demonstrated that higher GPC-3 expression level in HCC was a risk factor for shorter overall survival and GPC-3 expression level in poorly-differentiated tumor cells was higher than that in moderately- and well- differentiated HCC." (PMID 32605628, 2020). "Results from a phase I study evaluating GPC3 CAR-T cells in refractory or relapsed GPC3+ patients showed a slowdown in tumor progression (NCT02395250)." (PMID 32164265, 2020). "GPC3 was found significantly (p ≤ 0.01) overexpressed in all tumours by 68-, 50- and 96-folds in first, second and third tumours, respectively." (PMID 32203212, 2020). "Recent research has demonstrated that GPC3 is involved in the proliferation, differentiation, and adhesion of tumor cells, so it has a significant role in tumor growth and metastasis." (PMID 32582830, 2020). "More importantly, large numbers of cells in the tumor tissue showed co-staining for GPC3 and GFP, suggesting that these HCC cells originated from BMDCs of donor mice, but not the recipient mouse livers." (PMID 32296582, 2020). "Many of the genes upregulated in these tumor initiating cells were expressed in our Cluster 1 cells including Tff3, Tspan8, Gpc3, Ly6d, Cldn2." (PMID 33173221, 2020). "In this preclinical study, we report the ability of a novel radioimmunotherapy agent, combining the radionuclide 90Y with an HCC-specific antibody targeting the cell surface proteoglycan GPC3, to halt tumor growth in an orthotopic xenograft model." (PMID 31636665, 2019). "Global prognostic features included known prognostic markers in HCC, like alpha-fetoprotein and GPC3 expression in the tumor." (PMID 30922327, 2019). "In these cases, GPC3 was expressed in the primary tumor, but in recurrent cancer, the expression was undetectable." (PMID 31024850, 2019).
tumor (continued). "Our further study revealed that GPC3-Syn-IL12 NK92 cells secreted IL12 in a time-dependent manner after exposure to GPC3 antigen-positive tumor cells." (PMID 31921693, 2019). "The utility of GPC3 as a biomarker for predicting tumor recurrence and treatment efficacy is now being considered." (PMID 31024850, 2019). "GPC3 knockdown significantly suppressed the tumor growth and metastasis of LC cells, while forced expression of HIF-1α significantly reversed these effects." (PMID 31781603, 2019). "When GPC3 synNotch receptor expressing cells recognize tumor cells expressing GPC3 antigen, the transcription factor Gal4VP64 is separated from the receptor and thereby translocated into the nucleus regulating the expression of the reporter gene." (PMID 31921693, 2019). "It has been reported that the up-regulation of CK18, GPC3, and OPN are associated with increased tumor aggressiveness and poor prognosis." (PMID 30778112, 2019). "At the end of the experiments, the tumor weight in the combination group was also significantly less than that of the group treated with GPC3-28Z CAR-T cells." (PMID 31921693, 2019). "The prognostic significance of serum GPC3 levels and GPC3 immunoreactivity in tumor cells has been defined in patients with HCC." (PMID 31510063, 2019). "When the tumor volumes reached approximately 200 mm3, mice were grouped and treated with GPC3-28Z CAR-T cells or GPC3-Syn-IL12-NK92 cells or their combination in a 1:1 ratio." (PMID 31921693, 2019). "GPC3 regulates both stimulatory and inhibitory signals so it can either act as a tumor suppressor or an oncogenic protein and therefore plays a key role in regulating cancer cell growth." (PMID 31053802, 2019). "Our results here did indicate that the combined treatment with GPC3-28z CAR-T cells and GPC3-Syn-IL12 NK92 cells had better antitumor activities than the single drug treatment in mice bearing GPC3-positive tumor xenografts." (PMID 31921693, 2019). "Several studies have shown that expression of GPC3 regulating tumor proliferation and progression through Wnt signaling cascades." (PMID 31428581, 2019). "Univariate and multivariate analysis revealed that AFP, tumor diameter, vascular invasion and cytokeratin-19/glypican-3 sub-typing were independent prognostic factors for RFS, thus comprised the risk scoring model." (PMID 31676847, 2019). "In a mouse model of a GPC3-overexpressing liver tumor, anti-mouse GPC3 monoclonal antibody showed more potent anti-tumor activity when combined with anti-mouse PD-L1 antibody." (PMID 31510063, 2019). "We used GPC3-positive tumor cells SK-Hep-1-GPC3 to stimulate NK92 cells and found that GPC3-Syn-IL12-NK92 cells secreted an increasing amount IL12 with the extension of co-culture time and IL-12 expression reached steady-state expression by 24 h." (PMID 31921693, 2019). "In contrast to that, cancer vaccines targeting individual tumor-associated antigens (TAAs), such as NY-ESO1, glypican-3 (GPC3), and alpha-fetoprotein (AFP), have met with limited success in HCC." (PMID 31816940, 2019). "Since an effective tumor marker should be instinctively higher in cancer patients, we chose GPC3 and SPP1 for further analysis." (PMID 31635078, 2019). "In this study, we evaluated the expression of GPC3 on serum-derived exosomes and corresponding primary tumor tissue in patients with GEA." (PMID 31100935, 2019). "The tumor lesions exhibited cellular atypia with large nuclear, trabecular structures, and fatty changes and showed immunoreactivity for GS, GPC3, HSP70, and ARG1." (PMID 31238892, 2019). "GPC3 has been found to be significantly upregulated in HCC tumor cells, with around 80% positivity rate in HCCs28." (PMID 31819089, 2019). "GPC-3 has been suggested to be a tumor marker for hepatocellular carcinoma, and is reportedly expressed in several other tumors, including ovarian clear-cell carcinoma, neuroblastomas and Wilms’ tumors (see17 and references therein)." (PMID 31391540, 2019).
tumor (continued). "In vitro, ERY 974 activated T cells in a GPC3-dependent manner and showed anti-tumor effects on various solid cancer cells expressing GPC3, including HCC." (PMID 31510063, 2019). "To control the expression of IL12, we then engineered NK92 cells with anti-GPC3 synNotch receptors to produce IL12 (“GPC3-Syn-IL12-NK92”) in the presence of GPC3-positive tumor cells." (PMID 31921693, 2019). "The expression of GPC3 is silenced partly by promoter hypermethylation in some cancers, and DNA hypermethylation can be induced by tumor hypoxia." (PMID 31706332, 2019). "Combined CK19/GPC3 sub-typing, pre-transplant AFP level, tumor diameter and vascular invasion for novel risk score model were devised." (PMID 31676847, 2019). "Intriguingly, our evaluation between the expression of GPC3 and histopathological data revealed high expression of tissue-derived GPC3 correlated with a lower tumor grade." (PMID 31100935, 2019). "In conclusion, our biomarker analyses suggest the requirement of tumor GPC3 and blood CD16 as the necessary biomarker to achieve codrituzumab efficacy under the context of adequate codrituzumab exposure." (PMID 29535817, 2018). "When a tumor cell is expressing GPC3 on the surface, codrituzumab binds GPC3 and uses its Fc portion to recruit FcR(Fc receptor)-bearing NK cells to kill the tumor cell." (PMID 29535817, 2018). "Based on this mechanism, tumor GPC3 expression and CD16 expression on NK cells, which are the effector cells of ADCC, were investigated to correlate with codrituzumab's clinical efficacy in patients with advanced HCC." (PMID 29535817, 2018). "GPC3 expression in baseline tumor biopsies was determined by immunohistochemistry (IHC) analysis, and baseline CD16 expression on NK cells were quantified by peripheral blood lymphocyte immunophenotyping." (PMID 29535817, 2018). "The mechanism is that in vivo transfer of glypican-3-transfectant ES-DC (ES-DC-GPC3) elicit specific CTLs, a protective effect against ovalbumin-expressing tumor cells." (PMID 30135409, 2018). "Tumor cells were positive for hepatocyte, glypican-3, and pan-CK, and focally positive for CK20 and CEA but were negative for CK7 and TTF-1, CA 19-9, p63, CDX2, and OCT3/4." (PMID 30268151, 2018). "In CRC, downregulation of GPC3 mRNA levels was observed in all 10 tumor samples, compared to normal mucosa." (PMID 30027065, 2018). "The degree of tumor uptake on SUVmax and soluble GPC3 values at baseline tend to correlate, especially soluble GPC3 values measured using anti-GPC3 C-terminal mAb pairs for codrituzumab, which showed higher correlation." (PMID 29508107, 2018). "The result of our analyses agreed with the potential mechanism of codrituzumab-induced ADCC through recruitment of NK cells, which subsequently induces GPC3-positive tumor cell death." (PMID 29535817, 2018). "Tumor growth was significantly (P < 0.01) inhibited in mice treated with GPC3-CAR T cells compared with those treated with UTD or PBS." (PMID 30327605, 2018). "Glypican-3 (GPC3) as tumor antigen was exploited to develop GPC3-targeted CAR-T cells for the treatment of HCC." (PMID 29796190, 2018). "Although our numbers are small, our findings suggest that the degree of tumor uptake is related to GPC3 antigen concentration." (PMID 29508107, 2018). "In the present study, although the antitumor activity of GPC3-CAR T cell with deficient PD-1 was CAR-dependent, its off-tumor toxicity cannot be excluded in clinical therapy." (PMID 30327605, 2018). "As reported, the increased expression of Glypican-3 in tumor tissues was closely related to the level of EMT markers and to the cancer vascular invasion." (PMID 30046595, 2018). "The biotinylated L5 peptide was administered first to bind GPC3 on tumor cells (pretargeting), and then, SA-NPs were administered to chase the biotinylated L5 peptide." (PMID 30275801, 2018).
tumor (continued). "Using univariate and multivariate analysis, cytokeratin-19 and glypican-3 expression patterns, tumor number and histological grading from eight putative prognostic factors comprised the risk factor scoring model to predict the tumor recurrence." (PMID 28968990, 2017). "On the 10th day after vaccination, we checked the differences in the tumor sizes of P.y-GPC3-infected mice and control mice." (PMID 28445973, 2017). "Our data show that the tumor suppressor effect of miR-4510 is related to the reduction of GPC3 but also to Wnt signaling inactivation." (PMID 28476031, 2017). "Specifically, Glypican-3 and Hsp70 expression was increased and Glutamine synthetase became aberrantly expressed as tumours developed." (PMID 28128200, 2017). "We further show that the tumor suppressive effect of miR-4510 is mediated through direct targeting of GPC3 mRNA and inactivation of Wnt/β-catenin transcriptional activity and signaling pathway." (PMID 28476031, 2017). "The regression analysis showed that the two risk factors, including CK19/GPC3 expression pattern and AFP cutoff of ≥321 ng/mL, were the independent predictors of tumor recurrence." (PMID 28276470, 2017). "Combing CK19/GPC3 sub-typing, histological grading and tumor number into MC, the novel model significantly improved the stratification for early recurrence in patients fulfilling the MC after RR." (PMID 28968990, 2017). "The KD values of HN3-mPE24 and HN3-HN3-mPE24 for GPC3-expressing tumor cells were 12 nM and 1.4 nM, respectively." (PMID 27419635, 2017). "Previous studies have reported the discrepancy between tumor GPC3 expression and circulating levels of GPC3." (PMID 28378832, 2017). "The Ki67 expression in the tumor was also dramatically inhibited in both of P.y-GPC3 and P.y-WT vaccinated mice (P ≤ 0.001)." (PMID 28445973, 2017). "In a proof-of-concept study, we made HN3-PE38, an anti-GPC3 immunotoxin that has anti-tumor activity in HCC." (PMID 27419635, 2017). "Vaccination with P.y-GPC3 led to the activation of immunological mechanisms in killing or controlling the growth of tumor cells." (PMID 28445973, 2017). "The growth of tumor cells was clearly suppressed in the P.y-GPC3 infected mice group compared to those tumors in the P.y-WT (P < 0.05) and the control mice group (P≤0.001)." (PMID 28445973, 2017). "Together, our studies clearly indicate that anti-GPC3 is a promising anti-tumor reagent, especially for patients with HCC." (PMID 28881778, 2017). "With the combined detection of CK19 and GPC3, the significance of differentiation status of tumor cells was first revealed in the assessment of aggressive biological behavior of tumor cell." (PMID 26977595, 2016). "We also show that GPC3-CAR T cells suppressed tumor growth but with different efficacies in the PDX models of the three individual patients." (PMID 28123387, 2016). "Increasing oncofetal GPC-3 expression was detected during the malignant transformation of rat hepatocytes, with brown granule-like staining localized in tumor parts of atypical hyperplasia." (PMID 27286460, 2016). "Our observations have indicated the therapeutic value of HS20 because the antibody functions as a novel Wnt-blocking molecule by binding tumor-specific GPC3 instead of conventional Wnt or Frizzled molecules." (PMID 27185050, 2016). "GPC3 silencing activated growth, cell death resistance, migration, and invasive/metastatic capacity of MCF-7 cancer cells, while GPC3 overexpression inhibited these properties in MDA-MB231 tumor cell line." (PMID 27507057, 2016). "The reported discrepancies reinforce the idea of the GPC3 tissue specific role, highlighting once more the importance of tumor microenvironment." (PMID 27507057, 2016). "GPC-3 gene is located in upstream of the Wnt signal pathway that is involved in the initiation, generation, and tumor development, and up-regulated in HBV-related liver malignancies." (PMID 27286460, 2016).
tumor (continued). "On the other hand, in cancers originated from tissues that are GPC3-positive in the adulthood, the expression of GPC3 is reduced during tumor progression." (PMID 27507057, 2016). "In our mouse studies with hYP7, we did not observe a statistical difference between the 20 mg/kg and 60 mg/kg group, suggesting that 20 mg/kg dose fully covered the exposed GPC3 on the tumor cell surface." (PMID 27667400, 2016). "HCCs with microscopic vascular invasion had high mRNA levels of HAPLN1, LGR5, LEF1, SOX9, CD44, Glypican 3 and larger tumor size." (PMID 27191501, 2016). "The IHC results showed that there were very few GPC3-positive tumor cells in the group of CARgpc3 T cells compared with the control groups (treatment with Mock, 2D3–28BBZ CAR T cells or saline alone)." (PMID 26684028, 2016). "In the present study, the correlation between the immunosubtyping method of HCC based on the CK19 and GPC3 expression profiling and biological behavior of tumor cells were investigated." (PMID 26977595, 2016). "Next, we examined GPC3-positive tumor cells in the treated tumor sections by IHC and Western blot analysis." (PMID 26684028, 2016). "In summary, depending on the tissue, GPC3 displays a very different pattern of expression during tumor progression." (PMID 27507057, 2016). "Given that the MDA-MB231 malignant tumor cell line presented the lowest level of GPC3, we chose this cell line to overexpress GPC3." (PMID 27507057, 2016). "Tumor growth was efficiently suppressed by intravenous injection of 5 × 106 GPC3-CAR T cells (n = 5), as compared to a control group that received Control transduced T cells (n = 5)." (PMID 28123387, 2016). "In this context, it is, however, worth noting that GPC3 has also been proposed to act as a potential tumour suppressor in certain neoplasia, showing a putative transformation-dependent silencing of the glypican." (PMID 25935541, 2015). "The results demonstrated that DCs-GPC3 significantly promoted the autologous CIKs differentiation, as well as anti-tumor cytokine interferon-γ secretion." (PMID 25625609, 2015). "In this pilot study, a statistically significant up-regulation of NOTUM and GPC1 ( p-value < 0.0001) and down-regulation of GPC3 ( p-value < 0.001) mRNA levels were observed in all tumor samples." (PMID 26517809, 2015). "In conclusion, our study suggests that GPC3 is involved in tumor cell motility via HS chain-mediated coordination with the HGF/Met pathway." (PMID 26332121, 2015). "The in vivo data indicated that DCs-GPC3-CIKs exhibited significant HepG2 cell-induced tumor growth inhibition in nude mice." (PMID 25625609, 2015). "On this basis, our data on Glypican-1 and Glypican-3 dysregulation are of high interest, as they can help depict a more comprehensive picture of Wnt signal modulation in the tumor microenvironment." (PMID 26517809, 2015). "The location of the HCC tumor was verified using the IHC of the HCC marker GPC3 coupled with hematoxylin/Eosin staining." (PMID 25607934, 2015). "Enhancing GPC3 peptide vaccine therapy is considered to be promising in terms of sustained tumor control in HCC patients." (PMID 25354479, 2015). "Recent reports have indicated that Glypican-3 displays a tissue-specific pattern of expression during tumor progression." (PMID 26517809, 2015). "We demonstrated that the expression of several biomarkers used to detect HCC in humans, such as Gpc3 and Afp, is also upregulated in this tumor model, providing evidence at the molecular level that the tumorigenic process resembles human HCC." (PMID 26167473, 2015). "The tumor volume and weight were found to be the highest in the DCs-GPC3-CIKs group, followed by the DCs-CIKs, CIKs and PBS control groups." (PMID 25625609, 2015). "Glypican-3 has been shown to be an inhibitor of cell proliferation, and it can induce apoptosis in certain types of tumor cells." (PMID 26517809, 2015).